CD4 (CD4 molecule)
Diseases named in the same sentence as CD4 in open-access papers (continued):
Sharing a sentence is not in itself a finding about the gene and the disease.
cancer (continued). "This body of work indicates that CD4+ T lymphocytes may play a key role in enhancing cancer immunotherapy." (PMID 30140266, 2018). "We note that most of the T-cell response in the personal cancer vaccine trials was to CD4 T-cells." (PMID 30478295, 2018). "Paradoxically, inhibiting ITK in T cells may be efficacious in cancer, as this may enhance Th1-skewing of CD4+ T-cells and thereby improved memory formation and functionality of CD8+ T-cells, potentially leading to improved anti-tumor immunity." (PMID 29455639, 2018). "Cancer CD4, CXCL13, and FOXP3 expression correlated positively with each other (P ≤ 0.001)." (PMID 29482642, 2018). "Moreover, cancer septic animals exhibited expansion of two distinct subsets of CD4+ T cells relative to previously healthy septic controls." (PMID 29338031, 2018). "Moreover, a combination of IL-6 secreted by CD4+ T cells and growth-induced solid stress further contributes to the regulation of cancer cell morphogenesis, EMT and acquisition of a stemness phenotype." (PMID 28846080, 2017). "Moreover, elimination of CD4+&CD25+ Tregs in advanced cancer patients promoted efficacy of T cells and NK cells." (PMID 28029650, 2017). "Therefore, the use of CD4+ T cells to fight cancer has been proposed as an alternative approach and proven to have promising effects." (PMID 29250133, 2017). "Therefore, to overcome poor clinical outcomes of cancer vaccination, helper peptides that elicit CD4+ Th1 cells should be considered." (PMID 28321480, 2017). "The role of human CD4+ T cell subsets in cancer immunotherapy is still unclear." (PMID 29213079, 2017). "Importantly, the anti-cancer efficacy of TH9 cells was superior to all other CD4 T cell subsets tested, including TH1 and TH17 cells." (PMID 27832300, 2017). "CD4+ T helper cells are a valuable component of the immune response towards cancer." (PMID 27324616, 2017). "DCs present cancer cell antigens to CD4+ T cells through Jak-STAT signal transduction." (PMID 29133913, 2017). "The subtypes of lymphocytes, such as CD3+ T cells, CD8+ T cells, Th1 CD4+ T cells, and p46+ natural killer cells, are essential to the antitumor immunological reaction and have been proved to improve the survival of patients with malignancy." (PMID 28077792, 2017). "The function of CD4+CD25+Foxp3+Tregs in cancer had been described as highly variable." (PMID 28529951, 2017). "Nevertheless, our study suggests that blocking naive CD4+ T cell recruitment and conversion to Tregs in tumors could be an attractive new immune therapeutic strategy for cancer." (PMID 28290464, 2017). "As T helper cells, CD4+ T cells play an important role in anti-cancer immunity." (PMID 28687760, 2017). "Hence, EGCG can be considered an epigenetic regulator of the key players accomplishing SOCE in murine CD4+ T cells, Jurkat T cells and other cancer cells, i.e. STIM1/2 and Orai1." (PMID 29163766, 2017). "Therefore, we sought to optimize the CD4-zeta CAR based on lessons learned from cancer-specific CARs, in order to augment control over HIV replication." (PMID 29023549, 2017). "The patients with a high expression level of PD-1 on CD4+ T cells might be unable to maintain the response of adaptive immune cells against cancer by vaccination." (PMID 28241889, 2017). "Indeed, as follows from most studies, in which apoptosis-related markers were measured in CD4+ and CD8+ subsets of circulating T cells of cancer patients, CD8+ lymphocytes are more susceptible to apoptosis." (PMID 29075318, 2017). "Therefore, the ratio of Tregs to CD4+ T cells was higher than the normal range in 74.6% (97/130) of cancer patients." (PMID 28529951, 2017). "Reprogramming of Treg cells by a CD25 neutralizing antibody daclizumab results in an increase in CD56bright natural killer cells and functional T cells such as cytotoxic CD8+ T cells and CD4+ T helper cells in a small clinical trial of metastatic breast cancer patients who receive a cancer vaccine." (PMID 29379802, 2017).
cancer (continued). "Moreover, the percentages of CCR9+CD8+ and CCR9+CD4+ lymphocytes were lower in carcinoma tissue as compared to unaffected tissues." (PMID 29020986, 2017). "Similarly, we tried to induce of cancer antigen-specific CD4+ T cell lines by using CD14-ML-DC derived from cancer patients." (PMID 27050553, 2016). "Among ART‐treated patients who had “normalized” their CD4 count (>500 cells/mm3), KS incidence was considerably lower (31/100,000 person‐years) but, again, still comparable to other important cancers (e.g., pancreas, stomach, and colon) as measured in resource‐rich regions." (PMID 26823008, 2016). "CD4+CD25hiCD39+ T cells may have more immunosuppressive function through production of adenosine, and they have been found in increased levels in cancer patients." (PMID 27330811, 2016). "Cancer tissues had increased recruitment of CD4+ T helper cells." (PMID 26964534, 2016). "This approach could also be useful in cancer vaccinology, which often faces additional hurdles of targeting ‘modified self’ antigens where a humoral response is likely to be limited by CD4+ T cell deletion or tolerance." (PMID 27861512, 2016). "Yet our results enable the speculation that a proportion of long-surviving CD4+ T cells transferred into a cancer patient could, theoretically and eventually, become polarized to a Th2 phenotype." (PMID 27177227, 2016). "Our studies suggest that B cell depletion may have beneficial effects when incorporated into a cancer immunotherapy regimen that generates de novo CD4+ T cell responses." (PMID 27121060, 2016). "Meanwhile, CD4+ T cells play a central role in orchestrating the immune response to cancer." (PMID 26510910, 2016). "The largest study of 399 cancer patients on CD4+ and CD8+ apoptosis could predict late-toxicity yet failed to predict therapy outcome." (PMID 27340400, 2016). "In addition, cancer septic mice had a higher frequency of annexin-positive staining CD4+ lymphocytes compared to previously healthy septic mice, suggesting increased apoptosis was responsible for the loss of CD4+ cells." (PMID 27018973, 2016). "In addition, we did not detect a difference in expression of the Th2 marker CCR4 but did observe decreased production of the Th2 effector IL-4 from CD4+ cells taken from cancer septic mice." (PMID 27018973, 2016). "In addition to CD8+ CTLs, various CD4+ T cells, including regulatory T (Treg) and T helper 17 (Th17) CD4+ T cell subsets have emerged as key players across a variety of diseases involving inflammation, including cancer." (PMID 27784305, 2016). "Previous studies showed that a plasmid encoding a mutated murine BORIS (pmBORIS) DNA vaccine could induce murine CD8+ and CD4+ T lymphocyte responses and exhibited an anti-cancer effect." (PMID 26849232, 2016). "Furthermore, recent reports reveal that the activation of CD4+T cells is required for the immunization of the CD8+T cells against cancer." (PMID 27564277, 2016). "A CD4/CD8 ratio < 0.5 could identify patients who require a more intensive strategy of cancer prevention or screening." (PMID 27548257, 2016). "We show here for the first time that patients with multiple indications of advanced cancer had higher activation markers involved in immune checkpoint pathways in CD4+ and CD8+ T cells, several higher suppressive Treg and MDSC subsets, and altered expression of PD-L1 on APCs." (PMID 28936253, 2016). "Depletion of CD4+CD25+ T cells was a potential strategy for cancer treatment." (PMID 26462021, 2015). "Neutrophils may influence the recruitment and function of CD8+ and CD4+ T lymphocytes, both important cells in the cancer microenvironment." (PMID 26467671, 2015). "In addition to the recognized function of cytotoxic T lymphocytes (CTLs) in immune response to cancer, it is now clear that CD4+ T helper lymphocytes can also participate in the generation of antitumour immunity." (PMID 26081906, 2015).
cancer (continued). "In addition, a recent report indicated increased MDSCs and PD-1+ CD4 T cells in cancer patients receiving chemo-radiotherapy, which provides a rationale for combined treatment with chemo-radiotherapy and PD-1 blockade." (PMID 26573233, 2015). "However, the influences of age-related changes in CD4+ T-cell-mediated immune responses on the effectiveness of cancer immunotherapy are obscure because much of our understanding about antitumour immunotherapy is based on studies with young animals." (PMID 25850032, 2015). "However, another recent study demonstrated that CD4+CD25highTreg expansion and IL-10 secretion is promoted by cancer cell-secreted miR-214 that targets PTEN in CD4+ T cells." (PMID 28936238, 2015). "In line with this, our data gives evidence that compared with MMR proficient cancers, MMR-deficient tumors present a more frequent infiltration of cytotoxic CD8 cells and Th1 CD4 cells that might indirectly promote the antitumor immune response." (PMID 26496037, 2015). "Reversed CD4+/CD8+ ratios have been correlated with different outcomes in various cancers." (PMID 25605488, 2015). "In addition to cell number increases, CD4+ T cells changed their dominant subsets from Th1 in the early stages to Treg and Th17 cells in the late stages of the cancer progression." (PMID 25968569, 2015). "Cancer patients can have survivin specific CD4+ T cells and robust CD4+ responses may be generated with survivin HLA-class II restricted peptide vaccines in cancer patients." (PMID 25992291, 2015). "In addition, cancer-specific survival rates for patients were analyzed in correlation with T cells (CD4+, CD8+, FoxP3+ and IL-17+ T cells)." (PMID 25968569, 2015). "Overall, we suggest that a rational design of cancer immunotherapy mediated by CD4+ T cells in the elderly can be administered concurrently with temporal neutralization of IL-6 activity to restore the defective Th1 development without adversely affecting their antitumour activities." (PMID 25850032, 2015). "CD4+ T cell responses to all 7 different peptide pools were detected in cancer patients." (PMID 24520352, 2014). "We have shown that TSDR-demethylated CD4+ lymphocytes amplify the association of higher proportions of Tregs in KTRs with cSCC compared to those without cancer." (PMID 25250867, 2014). "Additionally, we found that (a) Mesothelin-specific T cell responses are significantly expanded in cancer patients (p = 0.0053), (b) the multifunctional CD4+ T cell response is directed toward a broad repertoire of epitopes within the Mesothelin protein." (PMID 24520352, 2014). "In addition to its expression in PD-1+ MP CD4+ T cells, which is suggestive of a function in age/cancer-induced immunosenescence, C/EBPα is also expressed in double negative (DN) 1–4 T cells." (PMID 24404186, 2014). "Indeed, in chronic inflammatory situations such as cancer, the presence of chronic antigen stimulation leads to an exhausted or senescent memory phenotype of CD4+ T cells." (PMID 25170840, 2014). "Finally, using MHC class I-molecule and MHC class II-molecule restricted TCR-transgenic mice specific for the Dby H–Y antigen, CD4+ T cells were found to be more efficient at eradicating cancer cells than CD8+ T cells in a side-by-side comparison." (PMID 24782871, 2014). "Rv0652-DCs could be used in cancer immunotherapy to indirectly potentiate CD4+ T cell differentiation towards a Th1 phenotype, leading to the production of IFN-gamma and direct activation of OVA-specific CD8+ T cells." (PMID 25102137, 2014). "Besides macrophages, CD4+ regulatory T cells can contribute to carcinogenesis by curtailing the efficacy of T cell immune responses against cancers." (PMID 24465869, 2014). "In addition to the age-related alterations within the CD4 compartment, it has recently been described that regulatory T cells accumulate in aged mice and cancer patients." (PMID 24404186, 2014).
cancer (continued). "Thus, understanding the role of CD4+ help in the expansion and effector function of these bystander cells has important implications for both cancer immunotherapy and viral immunity." (PMID 25119341, 2014). "In summary, the development of mRNA electroporated moDCs simplified anti-cancer immunotherapy significantly as transfection of DCs not only induces a broad, HLA-independent CD4+ and CD8+ immune response but also reduces the time and costs for vaccine preparation." (PMID 24782868, 2014). "The CD4+ T cells generated against these antigens were supposed to secrete interleukin (IL)-2 and pro-inflammatory cytokines, and to further activate the injected DCs, leading to an improved priming of cancer-specific CTLs." (PMID 24782868, 2014). "Importantly, the proportion of FOXP3+ CD4+ cells remains stable, making it suitable for use as a biomarker for cancer posttransplantation." (PMID 25250867, 2014). "However, the role and relative contribution of CD4+ T cells to immune responses generated against cancer in vivo in response to active vaccination remains to be fully elucidated." (PMID 24066030, 2013). "There is a growing appreciation that persistently low CD4+ T cell counts during treatment are associated with an increased risk of non–AIDS-related morbidities (e.g., cardiovascular disease, liver disease, and cancer) and death." (PMID 24391889, 2013). "In contrast, several recent lines of evidence suggest that a low-dose chemotherapy may display positive immunological effects during cancer therapy by depleting immunosuppressive cells such as CD4+ CD25+ regulatory T cells and myeloid-derived suppressor cells." (PMID 24133631, 2013). "We suggest that the major importance of CD4 T cell recruitment will be that they provide a cytokine milieu that facilitates the generation of endogenous responses against multiple class I MHC-restricted cancer antigens." (PMID 23970885, 2013). "One of the first attempts to distinguish between pTreg conversion and tTreg expansion in cancer was pursued by Bui and colleagues who adoptively transferred CD4+CD25+ cells, mixed at 1:10 ratio with CD25-depleted Thy1.1-congenic splenocytes, into immunodeficient mice bearing a progressive sarcoma." (PMID 23986759, 2013). "A recent study in mice revealed that the efficacy of therapeutic cancer vaccination in mice could be enhanced by removing CD4+CD25+ Treg, suggesting T cell signal transduction played a role in immunosuppressive effect." (PMID 23825635, 2013). "Here, in a larger cohort of subjects including both volunteers and cancer patients, CD4+ cells segregated distally from the CD14+HLA-DRlo/neg phenotype and were inversely correlated to the percentage of CD14+HLA-DRlo/neg monocytes (p < 0.001; Spearman r = -0.3244)." (PMID 25512872, 2013). "Furthermore, recent reports reveal that activation of CD4+ T cells is required for immunization of CD8+ T cells against cancer." (PMID 24223776, 2013). "In sensitivity analyses with an endpoint of cancer-specific mortality (right-hand side), we found similar associations to those seen for all-cause mortality for gender, smoking status, year of diagnosis, HBV status, CD4 count at diagnosis and type of cancer." (PMID 24106926, 2013). "A strong colocalization of ThPOK with CD4 both in NM and in MA was observed, weaker in carcinomas." (PMID 23349906, 2013). "An intriguing result from our study was that post-surgery cancer patients had significantly higher levels of recently activated effector CD4+ T cells as well as Tregs (CD38+) than controls, and they remained significantly increased until the completion of the study (18 weeks)." (PMID 24213326, 2012). "Taken together, these results and our observations suggest that the use of supplemental CD4+ T cell therapy or of CD4+ T helper factors may be beneficial for successful treatment of AdV-immunized patients with chronic infections or malignancies." (PMID 23071696, 2012).
cancer (continued). "Indeed, identified detectable numbers of specific CD4+ T cells both in cancer patients as well as healthy individuals." (PMID 22388712, 2012). "The CD4+ iNKT-cells have been found to be enriched in intrahepatic malignant tumors and could represent a new target for immunotherapy." (PMID 22396772, 2012). "By leveraging autologous CD4+ T cell help, aAPC/mOKT3 eliminates the use allogeneic feeder cells for T cell expansion, potentially increasing the availability of adoptive therapy as a cancer treatment." (PMID 22279573, 2012). "So, CD4+CD25+ regulatory T cells were further analyzed because they are able to inhibit antitumor immune response and thus, are associated with the progression of cancer." (PMID 22359669, 2012). "The role of CD4+ T and B lymphocytes is controversial in many cancers including STS." (PMID 22375962, 2012). "In that study, we immunized both Tg and wt mice with the human chemokine receptor CXCR4, which belongs to the G protein-coupled receptor (GPCR) family and plays important roles in the metastatic spread of cancer cells as well as in the entry of HIV in CD4+ cells." (PMID 22558422, 2012). "Thus, we believe that no significant autoimmune pathology would be elicited if STEAP or EZH2 CD4 T-cell epitopes were used for cancer immunotherapy." (PMID 22053850, 2011). "The low expression of CD4 molecules can weaken the immune activity fighting against cancer cells." (PMID 29147220, 2011). "The last CD4 cell counts before cancer diagnosis were 225, 521, 977 and 680/mm3." (PMID 21533035, 2011). "In contrast, spontaneous CD4+ T cell responses to MAGE-A3 were detected only in seropositive cancer patients but those to NY-CO-58 could be detected even in healthy individuals." (PMID 21858191, 2011). "Interestingly, the three controllers who experienced CD4 T cell declines below 200/mm3 and the four patients who developed cancer had all experienced blips." (PMID 21533035, 2011). "To determine whether the CD4+CD127lowCD25+/low Treg cells from cancer patients are functional, we used an in vitro suppression assay." (PMID 21904560, 2011). "Because previous reports have indicated that Treg populations can be increased in circulating lymphocytes from cancer patients as compared to healthy individuals, we compared the proportion of CD4+ T-cell subsets in circulating lymphocytes of EOC patients to healthy donors." (PMID 21829534, 2011). "Inclusion of the CD25low Treg-cell subpopulation in the enumeration of Treg cells by defining human Treg cells as CD4+CD127lowFOXP3+ demands the reassessment of Treg-cell frequencies in cancer patients as the actual frequencies were probably underestimated until now." (PMID 21904560, 2011). "Treg cells inhibit CD8+ and CD4+ T cells, which are major components of cancer immunosuppression." (PMID 20479946, 2010). "In late-stage cancer, the expression of IL-2 in CD4+ and CD8+ cells was also reduced." (PMID 21437225, 2010). "The mechanisms behind the antitumor effects of TAMs have not been fully elucidated and could potentially be ascribed to the M1 phenotype, which is in part controlled by the CD4+T cells and the death of cancer cells." (PMID 20141634, 2010). "In conclusion, successful cancer immunotherapy may depend on the ability to block upregulation of Foxp3 in effector CD4+ T cells and/or selectively inhibiting the expansion of a minor Treg subset." (PMID 21049016, 2010).